CD34 (CD34 molecule)
Diseases named in the same sentence as CD34 in open-access papers (continued):
Sharing a sentence is not in itself a finding about the gene and the disease.
tumor (continued). "Our IHC showed that CD34+ staining dynamics well matched the process of tumor vascularization during CRLM progression, whereas the positive staining of other endothelial cell markers, i.e., CD146 or CD31 did not." (PMID 36781833, 2023). "Morphometric analysis showed the significant increase of CD34+ into the tumor REL tissue (CD34: 0.51 ± 0.09%) as compared to the RESP samples, RESP (CD34: 0.2 ± 0.05%)." (PMID 37345141, 2023). "They observed that anti-PD-1 responses to the implanted tumor were better with engraftment of autologous then allogeneic CD34+ PBMC cells." (PMID 37509357, 2023). "While we were unable to fully match HLA genotypes of the engrafted CD34+ cells with the tumor implant, we did match HLA-A2 genotypes between tumor and the initial implantation into huNOG-EXL mice." (PMID 37509357, 2023). "Tumor tissues formed from MIIP-overexpressing MDA-MB-231 cells had decreased levels of CD34 and VEGFA, compared with that from control cells." (PMID 36130933, 2022). "The percentage of tumor area positive for CD34, considered as a surrogate for vascular density, was significantly higher in OGC-IC NST than in Ctl-IC NST (mean: 0.8% vs. 0.5%, p = 0.037)." (PMID 35697931, 2022). "A marker used to describe cancer cells stemness is CD34: Nrp1 was expressed the highest in CD34+ cells when compared to normal interfollicular keratocytes, hair follicle bulge stem cells, and CD34- tumor epithelial cells." (PMID 36203599, 2022). "Intense and widespread tumor cell expression of CD34 is an immunohistochemical characteristic of PLNTY, however no specificity." (PMID 35372027, 2022). "Immunohistochemical staining for CD34, smooth muscle actin, desmin, myogenin and protein S was performed, with positive staining found only for CD34 in the tumor." (PMID 35906668, 2022). "Current CAR T cells targeting CLL-1 and CD70 demonstrated cytotoxicity to tumor cells and spared CD34+ stem cells, indicating the potency of clinical implications for these two CAR T-cell treatments." (PMID 35990606, 2022). "Immunohistochemically, the cells expressed vimentin and, especially in peri-genital tumours, were positive for smooth muscle actin; in 50% of the tumours, CD34 positivity and S-100 negativity were observed." (PMID 35906668, 2022). "GBM specimens were immune stained for CD34, to estimate the microvessel density in the tumor and in healthy zone." (PMID 36611806, 2022). "Smp24, a cationic antimicrobial peptide identified from the venom gland of the Egyptian scorpion Scorpio maurus palmatus, shows variable cytotoxicity on various tumor (KG1a, CCRF-CEM and HepG2) and non-tumor (CD34+, HRECs, HACAT) cell lines." (PMID 35878176, 2022). "Morphometric analysis showed the significant increase of CD34+ into the tumor tissue (CD34: 2.1 ± 0.3%) as compared to the healthy tissue, CTRL (CD34: 0.58 ± 0.09%)." (PMID 36611806, 2022). "Angiogenesis and apoptosis in LLC tumor tissues were examined by CD34 immunohistochemistry and TUNEL assays." (PMID 36224346, 2022). "The IHC and western blotting results showed that expression levels of COMMD3, HIF1α, VEGF and CD34 proteins in xenograft tumours from LV-Con group were significantly higher than those from LV-ShCOMMD3 group." (PMID 35399735, 2022). "CD34 was positive in a few tumor cells, and integrase interactor 1 (INI1) retained nuclear expression." (PMID 36726928, 2022). "The tumor was also tested by IHC staining to explore the protein expression levels of angiogenesis-related β-Catenin and CD34, and WB was used to detect the expression levels of β-Catenin and p-VEGFR2/VEGFR2 proteins." (PMID 36092163, 2022). "Anti-CD34, an antibody that is very sensitive to endothelial cell differentiation, stains tumour endothelial cells more strongly than normal endothelial cells." (PMID 35672771, 2022).
tumor (continued). "We also performed CD34 staining to assess microvessel density, α-SMA staining to label cancer-associated fibroblasts (CAFs), and CD163 staining to label tumor-associated macrophages (TAMs)." (PMID 35928724, 2022). "To gain insight into the mechanism of action of the observed synergistic effect, we performed immunohistochemical staining of CD8 and CD34 on paraffin embedded MCA205 tumor tissue sections from mice treated with anti-CTLA4 with or without propranolol." (PMID 35017664, 2022). "The effects of radiation on tumor blood vessels and TAMs were assessed by CD34 and F4/80 immunostaining, respectively." (PMID 35156493, 2022). "To confirm the anti-angiogenic effect of propranolol, we immuno-stained paraffin embedded tissue sections of MCA205 tumors for the endothelial marker CD34 and quantified the CD34-positive area in the tumor core, excluding necrotic areas." (PMID 35017664, 2022). "Another form of infiltration better described in the literature is the presence of clusters of neoplastic cells in the cortex adjacent to the primary tumor, which is better appreciated with CD34 immunostain." (PMID 36290809, 2022). "Regarding immunohistochemistry, the tumor tended to be positive for vimentin (100%; n = 35/35), CD34 (63.4%; n = 26/41), ER (50%; n = 16/32), and PR (53.3%; n = 16/30), while S-100 showed 91% negativity (n = 41/45)." (PMID 35860056, 2022). "The biopsy results revealed a mesenchymal malignant tumor, tumor cell cytoplasm transparent or red staining, some showed acinar arrangement, tumor cell immunophenotype: CK (−), Vim (+), CD34 (+), MyoD1 (plasma +), SMA (focal +), CD56 (−), CgA (−)." (PMID 36467475, 2022). "In these tumours, additional features including architectural clefting with the formation of cystic spaces, IHC with emphasis on CD34 and cytokeratin expression, and the co-existence of DCIS or IBC are used to differentiate these two entities." (PMID 34322734, 2022). "Staining for CD34 highlighted the extensively formed tumor vessels, particularly at the invasive tumor front (mean count of 39/10HPF)." (PMID 35798765, 2022). "Tumor cells were positive with regard to the membranous and cytoplasmic expression of CD34, bcl-2, and CD99 and furthermore showed nuclear STAT6 positivity (respectively)." (PMID 36428694, 2022). "(H) Quantification of the percentage of mice bearing liver metastases, as well as the percentage of tumor area and the number of cells expressing Ki67, CD34, F4/80, and CD3 per mm2 determined by IHC." (PMID 36281643, 2022). "The tumor or pathological characteristics were less reported to be related to GNT with CD34 expression." (PMID 36307486, 2022). "Regarding other immunocompromised mice, GVHD is more evident than that in CD34+ humanized mice despite the tolerance of human tumour cells." (PMID 36239215, 2022). "Some tumors block T cell homing by reducing the expression of adhesion molecules such as ICAM-1, VCAM-1, and CD34 on the tumor endothelium." (PMID 35211124, 2022). "First, using the CD34 immunostain as a surrogate marker, we showed that the proportion of tumor area occupied by vessels was statistically higher in OGC-IC NST and in OGC-MC than in their respective controls without OGC." (PMID 35697931, 2022). "Immunohistochemistry analysis of CD34 showed rNDV-VEGF-Trap significantly decreased the number of vascular endothelial cells in the tumor tissues." (PMID 35381011, 2022). "For its diagnosis, immunohistochemical markers such as cluster differentiation (CD) CD34 are used, which is strongly expressed by this tumor, to differentiate it from other cancerous tumors." (PMID 35414906, 2022). "Macrophages are mononuclear CD34+ antigen-presenting cells of defense mechanism and play dual roles in tumor burden." (PMID 36324077, 2022). "Histologically, the tumor was made up of spindle-shaped cells immunohistochemically positive for c-Kit and CD34." (PMID 35974415, 2022).
tumor (continued). "We confirmed the KS cells to be typical plump spindle tumor cells based on the CD34, which is an endothelial marker." (PMID 36316837, 2022). "Usually, it has been known that MVI site is characterized by invasion of tumor cells into the blood vessels that were coated with CD34+ endothelial cells." (PMID 35210426, 2022). "Tumor cells predominantly accumulated around the vessels (the so-called vascular co-option), and CD34+ cells were observed along the vessel walls." (PMID 35785200, 2022). "We showed VM structures in NPC tissue by double staining with PAS and CD34, in line with previous studies in other neoplasms." (PMID 35251967, 2022). "A high immunoexpression of CD34 in the vessels of tumor tissue indicates intensive neoplastic neovascularization and increased MVD." (PMID 35884977, 2022). "Clinical and pathological factors in 247 patients were compared between two groups [tumor with CD34 (+) vs. CD34 (−)]." (PMID 36307486, 2022). "Tumor sections from the propranolol treated group had a significantly lower CD34-positive area compared to the control group, confirming the anti-angiogenic effect of propranolol." (PMID 35017664, 2022). "Then we evaluated the inhibition of rNDV-VEGF-Trap on vascular endothelial cell proliferation in the tumor tissue by CD34 IHC assay." (PMID 35381011, 2022). "further reported that in vitro, NK cells lose their potent anti-tumor properties, as indicated by impaired cytotoxicity to CD34+ MDS blast cells, resulting in enhanced tumor evasion." (PMID 36569863, 2022). "Immunohistochemistry staining (magnification, ×400) showed that the tumor cells were positive for CD34, STAT6, Ki67 (8%), CD99, and Vimentin." (PMID 36386546, 2022). "The current results showed a considerable increase in the VEGF serum levels and count of CD34 in tumor tissues in untreated mice compared to normal, which corroborate previous studies." (PMID 35798765, 2022). "Immunohistochemistry revealed that the tumor tended to be positive for vimentin (100%), CD34 (63.4%), ER (50%), and PR (53.3%) while S-100 showed 91% negativity." (PMID 35860056, 2022). "Induction of tumor cell apoptosis; Downregulation of VEGF and CD34; Reduced tumor blood vessel formation." (PMID 35640930, 2022). "Immunohistochemistry showed that the tumor cells were diffusely positive for TLE-1 and vimentin and focally positive for epithelial membrane antigen, AE1/3, Cam5.2, SATB2, and CD34 (all in less than 10% tumor cells)." (PMID 35125107, 2022). "Immunohistochemistry reported tumor cells that are positive for smooth muscle actin and β-catenin (nuclear staining) and focally positive for CD34." (PMID 35638030, 2022). "To investigate changes in CSC behavior, we treated the tumor cells with cisplatin and observed that a new CD34+OV-6+ population emerged on a lower expression level." (PMID 36497307, 2022). "In relation to angiogenesis, GBM is characterized as very vascularized and from our evaluations, the quantity of CD34+ cells in the tumor mass resulted in times greater than in surrounding tissue." (PMID 36611806, 2022). "Intriguingly, a recent study reported that the tumor xenografts originating from CD34high-expressing GdECs showed a more undifferentiated phenotype compared with CD34-/low expressing cells." (PMID 36294763, 2022). "CTLA-4 gene is expressed in a variety of cells, including B cells, monocytes, granulocytes, CD34+ stem cells, and various tumor cells." (PMID 36147250, 2022). "Histopathological findings favored the diagnosis of GPC as it revealed tumor cells positive for smooth muscle actin and β-catenin with immunopositivity for CD34." (PMID 35638030, 2022). "Immunohistochemistry results of CD34 showed rNDV-VEGF-Trap significantly reduced the number of vascular endothelial cells in the tumor tissues of the tumor-bearing mice." (PMID 35381011, 2022).
tumor (continued). "The effect of SAR131675 on tumor vascularization, (angiogenesis and lymphangiogenesis) was studied using CD34 (progenitor endothelial cell marker) and podoplanin (a LEC marker)." (PMID 35681695, 2022). "To further examine the effect of each treatment on tumour‐associated vasculature, we analysed microvascular density (MVD) of each tumour sample staining for CD34." (PMID 34910361, 2022). "The outcomes of IHC staining also illustrated that the tumor staining intensity of β-Catenin and CD34 in the COMMD3-overexpressed group was higher than that of the control group, while the COMMD3-RNA interference group had lower intensity." (PMID 36092163, 2022). "Immunohistochemically, ERG (erythroblast transformation specific-related gene) and endothelial markers such as CD31 and CD34 show expression, indicating the endothelial origin of the tumor." (PMID 35252055, 2022). "Microscopic findings were that the tumor was made up of spindle-shaped cells, including nine mitotic figures per 50 high-power fields, immunohistochemically positive for c-Kit and CD34." (PMID 35974415, 2022). "Histology and confocal microscopy were used to examine the protein expression of CD34 and Ki67 in tumor tissue of different treatment groups." (PMID 36605098, 2022). "The inhibition of CD34+ progenitor-mediated vasculogenesis, likewise anti-angiogenic therapies, showed significant reduction in tumor neovasculogenesis and development." (PMID 36611906, 2022). "The CD34 is considered a specific marker for tumor angiogenesis, as it can identify the condition of new blood vessel formation during tumor growth." (PMID 35798765, 2022). "Expression of these markers was observed in the tumor cells of control and treated mice, with a tendency of the number of cells immunopositive for CD34 and VEGFR to decrease in the treated group." (PMID 33806229, 2021). "CD34 expression has been shown in 81–95% of SFTs cases, but its expression is lost, especially in malignant and dedifferentiated tumours." (PMID 34849218, 2021). "Mice treated with CD3+CD34+ cells transduced following IL-7 culture demonstrated a significant delay in tumor progression when compared to untreated mice (p = 0.0025)." (PMID 34172810, 2021). "Using high power resolution in the tumor area, we observed that GFAP expression was lower in the internal core of the tumor than in the peripheral area, CD34-positive vessels were surrounded by GFAP-positive astrocytes, and AQP4 was weakly expressed." (PMID 35083148, 2021). "In our case, CD34 was diffusely positive for most tumor cells, and fibroblast-like cells showed especially strong positive signals, and the tumor was well-bordered without encapsulation." (PMID 33429765, 2021). "In cellular blue nevus, the connective tissue between the compact, irregular tumor nests shows CD34+ cells, whose processes penetrate the peripheral areas of the tumor nests, dissecting small groups of tumor cells." (PMID 34298962, 2021). "In our observations, these cells have numerous processes, present mitosis and can lose CD34 expression in some cells or throughout the tumor." (PMID 34298962, 2021). "All five S100 IHC-positive OSCTs also had RNA expression levels for CD34 above the cutoff, supporting a differentiation toward a perivascular wall tumor phenotype." (PMID 34422947, 2021). "A study of this possibility to confirm resident CD34+SC/TC participation as precursors of stromal cells (CAFs) in tumours would be of interest." (PMID 33916213, 2021). "In line with the MOST imaging, CD34 staining demonstrated that treatment with RG@M-γ-CD CNPs efficiently blocked tumor angiogenesis." (PMID 33536421, 2021). "Here, GC tissue microarrays containing 75 tumor tissues and paired normal counterparts were used to assess the expression of Tagln2 in ECs, in which CD34 was used to specifically label ECs." (PMID 34150622, 2021).
tumor (continued). "Immunohistochemistry testing for tumour characterisation showed hematopoietic progenitor cell antigen (CD34) and signal transducer and activator of transcription 6 (STAT6) positivity in keeping with an SFT." (PMID 34812333, 2021). "Immunohistochemically, the tumor cells were positive for vimentin, smooth muscle actin (SMA), CD34, and epithelial membrane antigen (EMA); loss of the BAF47/INI1 protein in the tumor cells was also confirmed." (PMID 34193249, 2021). "Tumor cells demonstrate strong positive staining for vimentin, CD34, apolipoprotein D, and nestin when subjected to immunohistochemical studies." (PMID 33715634, 2021). "Further studies are required to resolve the HLA mismatch between CD34+-driven host immune cells and the grafting tumor." (PMID 34685714, 2021). "GC tissue microarrays containing 75 tumor tissues and paired normal counterparts from patients with available clinical data was used for IHC analysis of CD34 and Tagln2." (PMID 34150622, 2021). "CD34+SC/TC processes/telopodes were generally long and thin in the normal breast and in the stromal cells in tumours, whereas occasional observations in sections parallel to the surface of these processes had a flattened appearance." (PMID 33916213, 2021). "For instance, significant tumor growth delay following pembrolizumab therapy was shown in the Onco-HuNSG mouse model using allogeneic but HLA partially matched CD34+ human pluripotent stem cell (HPSC) donors and tumors." (PMID 34676046, 2021). "In detail, bacterial delivery of endostatin linked with RGD or PSMA scFv targeting peptides was shown to significantly decrease CD34 expression within the tumor, compared to treatment with PBS or Salmonella only." (PMID 35003007, 2021). "We found that the microenvironment score, matrix score, and immune score were higher, the tumor purity was significantly decreased, and the matrix content was increased in the group with high expression of CD34/CD276." (PMID 34307389, 2021). "In this report, vascular endothelial progenitor cells derived from CSCs were thought to be present in CD34+ cells and contribute to tumor angiogenesis." (PMID 34907219, 2021). "We describe the clinical presentation of this rare tumour of the sinonasal and oral cavity, including upper airway obstruction, and the importance of immunohistochemical markers such as CD34 and BCL-2 in diagnosing SFT." (PMID 34849218, 2021). "Tumor specimens of lean CRC patients displayed the presence of cells expressing CD34 + /CD31 + /CD45− ascribable to an endothelial phenotype." (PMID 34408135, 2021). "In pre-existing BVs completely co-opted by the tumor, the adventitia often appeared to be entirely free of CD34+ cells, while the media layer of the vessel wall composed mainly of smooth muscle cells remained largely intact." (PMID 34359889, 2021). "Intratumoral angiogenesis, as assessed by CD34 immunostaining of tumor sections, was found to be significantly increased in the BRCA1+/− iMSC treatment group." (PMID 33513753, 2021). "Activated CD34+SFCs/TCs are observed a short distance from the tumor components and show an increased somatic region with voluminous nuclei." (PMID 34298962, 2021). "Rather, AML and ALL samples had a significantly greater proportion of the genome that was marked by H3K27me3 than CD34+ cells, suggesting that these tumor types are more differentiated." (PMID 34663924, 2021). "A fact not previously considered is the presence of different size vessels, many of which are tiny and located at the center of each whorled arrangement of CD34+ stromal cells (tumor formed by perivascular CD34+ stromal cells)." (PMID 34298962, 2021). "CD34 expression was further evaluated by immunofluorescence analysis of both miPS-LLCcm cells and their tumor derived primary cultured cells." (PMID 34907219, 2021).